ENSG00000276490 (novel transcript)
Gene: Protein-coding gene on chromosome 10 (94,688,154 to 94,853,073, forward strand). Ensembl gene ENSG00000276490.
Genetic constraint (gnomAD): Missense variants: 415 observed, 385.46 expected, observed/expected ratio (o/e) 1.08, 90% interval 0.99 to 1.17. Synonymous variants: 151 observed, 134.38 expected, observed/expected ratio (o/e) 1.12, 90% interval 0.98 to 1.29.